DGUOK (deoxyguanosine kinase)
Description:
Phosphorylates deoxyguanosine and deoxyadenosine in the mitochondrial matrix, with the highest efficiency for deoxyguanosine. In non-replicating cells, where cytosolic dNTP synthesis is down-regulated, mtDNA synthesis depends solely on DGUOK and TK2. Phosphorylates certain nucleoside analogs (By similarity). Widely used as target of antiviral and chemotherapeutic agents.
Synonyms: DGK; MTDPS3; NCPH; NCPH1; PEOB4
Tractability: Small molecule: a structure with a bound ligand is known. PROTAC: ubiquitination databases record sites on it; its protein half-life has been measured.
Target class: Enzyme; Transferase
Gene: Protein-coding gene on chromosome 2 (73,926,794 to 73,958,961, forward strand). Ensembl gene ENSG00000114956.
Subcellular location: Mitochondrion
Pathways (Reactome):
Metabolism: Purine salvage
Gene Ontology:
Molecular function: deoxyadenosine kinase activity; deoxyguanosine kinase activity; protein binding; ATP binding; deoxynucleoside kinase activity
Biological process: dAMP salvage; purine deoxyribonucleoside metabolic process; guanosine metabolic process; carbohydrate derivative metabolic process; mitochondrial ATP synthesis coupled electron transport; negative regulation of neuron projection development
Cellular component: mitochondrion; nucleus; cytoplasm; mitochondrial matrix; cytosol
Genetic constraint (gnomAD): Loss-of-function variants: 26 observed, 32.37 expected, observed/expected ratio (o/e) 0.8, 90% interval 0.59 to 1.12. The upper end of that interval is the gene's LOEUF score, 1.12, which puts it in group 4 of 6, group 1 being the genes least tolerant of losing a copy. Missense variants: 352 observed, 338.8 expected, observed/expected ratio (o/e) 1.04, 90% interval 0.95 to 1.13. Synonymous variants: 142 observed, 127.89 expected, observed/expected ratio (o/e) 1.11, 90% interval 0.97 to 1.28.
Gene-disease validity (ClinGen):
ClinGen rates the evidence that DGUOK causes each of these diseases.
mitochondrial disease (autosomal recessive): Definitive.
Homologues: Orthologues: chimpanzee DGUOK (99% identical), macaque DGUOK (96% identical), dog DGUOK (84% identical), rabbit DGUOK (84% identical), pig DGUOK (83% identical), mouse Dguok (75% identical), rat Dguok (73% identical), guinea pig DGUOK (54% identical), tropical clawed frog dguok (50% identical), zebrafish dguok (49% identical). Paralogues in human: DCK (44% identical), TK2 (26% identical), NDUFA10 (19% identical).
Diseases named in the same sentence as DGUOK in open-access papers:
DGUOK is named in the same sentence as 66 diseases in open-access papers, as found by Europe PMC text mining. Sharing a sentence is not in itself a finding about the gene and the disease. The quoted sentences say what the papers report.
liver failure (16 papers, 2011 to 2024). A liver disease characterized by the liver losing or has lost all of its function. "The prognosis for DGUOK deficiency is poor; most affected children die of liver failure before 4 years of age." (PMID 39336844, 2024). "Research found that liver failure caused by mutations in the deoxyguanosine kinase (DGUOK) gene is closely related to ferroptosis triggered by iron overload." (PMID 39568773, 2024). "This case highlights the unpredictable evolution of children with LT for liver failure due to DGUOK deficiency." (PMID 39336844, 2024). "Patients with deoxyribonucleoside kinase (DGUOK) mutations usually die of severe liver failure before 2 years of age." (PMID 39872359, 2022). "Patients with variants in DGUOK producing mtDNA depletion present with early onset liver dysfunction and subsequent hepatic failure with co-morbid neurodevelopment delay, abnormal eye movements, and hypotonia." (PMID 33426505, 2020). "The classic features of deoxyguanosine kinase (DGUOK) deficiency are infantile onset hepatic failure with nystagmus and hypotonia; mitochondrial DNA studies on affected tissue reveal mitochondrial DNA depletion." (PMID 30956829, 2019). "The obtained data of the TK2−/− mice resembles symptoms seen in patients with progressive liver failure due to DGUOK deficiency that commonly present with hypoketotic hypoglycemia in combination with lactic acidosis and mild neurological involvement." (PMID 23505564, 2013). "Mandel and colleagues observed neuronal symptoms with increased lactic acid levels in 19 children with deoxyguanosine kinase dGUOK gene mutations and hepatic failure with reductions in activity of mitochondrial complexes I, II and IV." (PMID 22294875, 2011). "Most patients with DGUOK deficiency will develop life-threatening liver failure requiring LT." (PMID 39336844, 2024). "In addition, patients with DGUOK mutations show hepatic iron overload, which may progress to liver failure." (PMID 39872359, 2022). "Furthermore, the variant Q170R in DGUOK in heterozygous state has been detected in a cohort of 45 subjects with ALF of which one developed liver failure following exposure to isoniazid.To what extent this variant contributed to the APAP induced ALF in subjects #6 requires further functional studies." (PMID 27483465, 2016). "Our study provides the first hereditary liver disease model using pure hepatocyte organoids, giving critical mechanistic insight into liver failure of DGUOK mutant MDS." (PMID 34026460, 2021). "To determine the pathological mechanism of iron overload and lethal liver failure in DGUOK mutant MDS, we used ferric ammonium citrate (FAC) to induce iron overload." (PMID 34026460, 2021). "The infantile phenotypes of hepatocerebral forms of MDS associated with mutations in POLG, PEO1 (Twinkle), DGUOK or MPV17 have similarities, presenting with liver failure along with various neurological and endocrinological manifestations." (PMID 23714749, 2014). "Humans carrying TK2 deficiency primarily present with severe myopathy and display neurological phenotypes whereas DGUOK, POLG and MPV17 deficiencies have been associated with liver failure and encephalomyopathy." (PMID 23505564, 2013). "Sequencing of the DGUOK, POLG and MPV17 genes did not reveal the causative mutation, however, it is possible that the mtDNA depletion contributed to the liver failure in these patients." (PMID 27053192, 2016).
mitochondrial DNA depletion syndrome (16 papers, 2011 to 2024). The mitochondrial DNA (mtDNA) depletion syndrome (MDS) is a clinically heterogeneous group of mitochondrial disorders characterized by a reduction of the mtDNA copy number in affected tissues without mutations or rearrangements in the mtDNA. "Deoxyguanosine kinase (dGk) deficiency is one of the most common causes of hepatocerebral mtDNA depletion syndrome." (PMID 38756539, 2024). "Deoxyguanosine kinase (DGUOK) deficiency is one of the genetic causes of mitochondrial DNA depletion syndrome (MDDS) in humans, leading to the hepatocerebral or the isolated hepatic form of MDDS." (PMID 36709400, 2023). "While biochemical studies suggested a diagnosis of congenital HI, molecular genetic testing confirmed mtDNA depletion syndrome from DGUOK deficiency." (PMID 38027095, 2023). "Deoxyguanosine kinase (DGUOK)-related mitochondrial DNA depletion syndrome (OMIM# 251880) or DGUOK deficiency can present with hypoglycemia but has additional phenotypic manifestations." (PMID 38027095, 2023). "Mutation in DGUOK is well documented in patients with mitochondrial DNA depletion syndrome leading to neurological conditions with liver dysfunction." (PMID 33484326, 2021). "Taken together, the phenotypic screen using iPSC-derived DGUOK-deficient hepatocytes provides a variety of new perspectives in the identification of therapies for mtDNA depletion syndromes." (PMID 30404003, 2018). "Among these diseases, deoxyguanosine kinase (DGUOK) deficiency is the most common cause of hepatic mtDNA depletion syndrome and accounts for approximately 15%–20% of all MTDPS cases." (PMID 30404003, 2018). "Although in the context of the mtDNA depletion, oxidative phosphorylation activity is reduced, our results revealed an increase in ROS levels in the DGUOK-deficient hepatocyte-like cells, as has been described for other types of mtDNA depletion syndromes." (PMID 30404003, 2018). "There are as many as 112 infantile mtDNA depletion syndrome (MDS) cases in the literature related to DGUOK gene variants." (PMID 29137425, 2017). "For instance, iPSCs from patients with deoxyguanosine kinase gene (DGUOK) mutations, a major cause of mitochondrial DNA depletion syndrome, were used to create liver organoids, a model that includes both hepatocyte characteristics and the patient’s genetic background." (PMID 36875751, 2023). "Similarly, HCC was found in a patient with hepatocerebral form of mtDNA depletion syndrome caused by mutations in DGUOK gene responsible for mitochondrial salvage synthesis of deoxynucleotides." (PMID 22028711, 2011). "Although liver transplantation is considered, research has demonstrated that for patients with DGUOK-related mitochondrial DNA depletion syndrome and neurologic symptoms, early demise occurs." (PMID 38027095, 2023). "Mitochondrial DNA depletion syndrome (MDS) is a group of severe inherited disorders caused by mutations in genes, such as deoxyribonucleoside kinase (DGUOK)." (PMID 34026460, 2021). "Our studies reveal that DGUOK-deficient iPSC-derived hepatocytes recapitulate the pathophysiology of MTDPS3 in culture and can be used to identify therapeutics for mtDNA depletion syndromes." (PMID 30404003, 2018). "However, due to rapid genetic testing, both patients were found to have deoxyguanosine kinase (DGUOK)-related mitochondrial DNA depletion syndrome, an unexpected diagnosis." (PMID 38027095, 2023).
Nystagmus (6 papers, 2016 to 2021). Rhythmic, involuntary oscillations of one or both eyes related to abnormality in fixation, conjugate gaze, or vestibular mechanisms. "Mutations in the DGUOK gene encoding deoxyguanosine kinase were described in Israel, causing a severe hepatocerebral syndrome with neonatal liver failure, nystagmus, and hypotonia." (PMID 31718067, 2019). "Deoxyguanosine kinase (DGUOK) deficiency causes mtDNA depletion with a predominant liver phenotype though neurological features (nystagmus, muscular hypotonia, psychomotor retardation) often accompany this condition." (PMID 27053192, 2016). "Although liver disease is one of the primary clinical features and cause of death of MTDPS3, some of the DGUOK mutations lead to multisystem disorders with muscular or neurological manifestations, including hypotonia, psychomotor retardation, or nystagmus." (PMID 30404003, 2018).
liver disease (5 papers, 2016 to 2025). "Here, we establish an in vitro liver disease model of liver organoids and hepatocytes developed from iPSCs of DGUOK mutant patients, along with associated controls and isogenic cell lines corrected by the CRISPR/Cas9 system." (PMID 34026460, 2021). "This contrasts with the experience in ALF due to hepatocerebral MDS from bi-allelic mutations in POLG, DGUOK or MPV17 commonly manifesting as multi-system disorders before or shortly after onset of liver disease." (PMID 27483465, 2016). "While it is possible that HCC could be gene therapy related, as has been demonstrated in other mouse preclinical gene therapy studies, it should be noted that HCC is also a recognized complication of liver disease in patients with DGUOK deficiency." (PMID 39897640, 2025). "Depending on the type of mutations, DGUOK-related MTDPS, also called mtDNA depletion syndrome 3 (MTDPS3), can cause neonatal hepatic disorders or multisystem diseases." (PMID 30404003, 2018).
liver dysfunction (5 papers, 2016 to 2026). "Deoxyguanosine kinase deficiency is one of the most common subtypes, typically presenting with liver dysfunction in infancy and having a poor prognosis." (PMID 42094628, 2026).
hepatocellular carcinoma (4 papers, 2011 to 2020). A malignant tumor that arises from hepatocytes. "A possible link between mtDNA depletion and tumorigenesis has been suggested by the detection of hepatocellular carcinoma in a patient with DGUOK deficiency." (PMID 27053192, 2016). "Since then other reports also support a role for MPV17 and deoxyguanosine kinase SUCLA2 mutation induced hepatocellular carcinoma in MDS patients." (PMID 26468652, 2015). "Previous studies revealed that DGUOK mutation or deficiency is the most common cause of mtDNA depletion and is associated with various diseases, including neonatal hepatocerebral disease and hepatocellular carcinoma." (PMID 32766141, 2020). "However, our recent study revealed that infant patients with mutations in DGUOK (deoxyguanosine kinase) MPV17 genes had developed hepatocellular carcinoma (HCC)." (PMID 22028711, 2011).
lung carcinoma (4 papers, 2019 to 2024). "Overexpression of DGUOK has been associated with worse prognosis in lung cancer, and its depletion suppressed lung adenocarcinoma growth, CSC self-renewal and metastasis." (PMID 37260986, 2023). "The upregulation of DGUOK was associated with poor overall survival of the patients with lung carcinoma." (PMID 33392072, 2020). "To further determine the role of DGUOK in lung cancer progression, we investigated the correlation between DGUOK levels and clinicopathological parameters in a lung adenocarcinoma tissue microarray consisting of 113 tumor samples." (PMID 31633874, 2019). "DGUOK expression was highly elevated in lung adenocarcinoma when compared to paired adjacent lung tissues, indicating upregulation of DGUOK in lung cancer." (PMID 31633874, 2019). "Our data also indicate that DGUOK abrogation had little effect on lung cancer cell survival and proliferation." (PMID 31633874, 2019). "The restoration of mitochondrial OXPHOS in DGUOK KO lung cancer cells using NDI1 was able to prevent AMPK‐mediated phosphorylation of YAP and to rescue CSC stemness." (PMID 31633874, 2019). "Our data demonstrated that a 50–70% reduction in mtDNA in DGUOK KO lung cancer cells was sufficient to induced robust tumor regression and inhibition of CSC self‐renewal." (PMID 31633874, 2019). "In summary, using different assays for lung cancer CSC markers, our results consistently demonstrate a significant reduction in lung cancer CSC population after DGUOK KO." (PMID 31633874, 2019). "The decrease in respiratory complex proteins was further confirmed when a different sgRNA was used to knockout DGUOK (KO2) in lung cancer cells (Fig EV3A)." (PMID 31633874, 2019). "No tumor formation was detected in the DGUOK KO group at any dilution, supporting an essential role for DGUOK in the self‐renewal of lung cancer CSC." (PMID 31633874, 2019). "DGUOK depletion also significantly decreased the CD166+ population in lung cancer cells, further supporting that DGUOK depletion decreased the CSC population in lung adenocarcinoma." (PMID 31633874, 2019). "Here, we investigated the role of the DGUOK in the self‐renewal of lung cancer stem‐like cells (CSC)." (PMID 31633874, 2019). "Since mtDNA encodes 13 protein subunits essential for the respiratory complex biogenesis, we investigated the effects of DGUOK depletion on mtDNA levels in lung cancer cells." (PMID 31633874, 2019). "We chose NDUFB8 because this is one of the most dramatically down‐regulated complex I proteins in DGUOK KO lung cancer cells, and also because we were able to obtain an anti‐NDUFB8 antibody suitable for IHC staining." (PMID 31633874, 2019). "Our data further support that DGUOK targeting inhibits the self‐renewal of lung cancer CSC, mitochondrial respiration, and AMPK‐YAP signaling." (PMID 31633874, 2019). "The KO of DGUOK in these two cell lines dramatically inhibited the formation of tumor spheres and the expression of serum‐induced CK20, suggesting DGUOK is critical for the transdifferentiation of lung cancer cells." (PMID 31633874, 2019). "The expression levels of DGUOK were comparable between established lung cancer cell lines (H1650, A549) and PDCs (Fig EV2F)." (PMID 31633874, 2019). "The ectopic expression of YAP1‐6SA at least partially restored the lung sphere formation ability and the proportion of ALDH+ CSC in DGUOK KO cells (and EV4E), suggesting that DGUOK depletion inhibits lung cancer cell stemness by inhibiting YAP1 signaling." (PMID 31633874, 2019). "We further investigated the role of DGUOK in lung cancer tumor growth and metastasis in an orthotopic model." (PMID 31633874, 2019). "However, the role and mechanism of DGUOK in regulation of mitochondria function and lung cancer progression still poorly understood." (PMID 33392072, 2020). "Importantly, genetic targeting of DGUOK using inducible CRISPR/Cas9 was able to induce robust tumor regression in Lewi's lung carcinoma models." (PMID 31633874, 2019).
lung carcinoma (continued). "Taken together, our data support a role for DGUOK in lung cancer cell stemness." (PMID 31633874, 2019). "Pharmacological inhibitors targeting DGUOK could be useful in the treatment of lung cancer and the prevention of lung cancer recurrence." (PMID 31633874, 2019). "To test our hypothesis, we first assessed DGUOK level in a panel of lung cancer cell lines." (PMID 33392072, 2020). "However, the role and mechanism of DGUOK in lung cancer still poorly understood." (PMID 33392072, 2020). "Therefore, although DGUOK‐targeted therapies in lung cancer patients may have potential side‐effects on mtDNA homeostasis in the liver, these side‐effects are possibly tolerable within a therapeutic window." (PMID 31633874, 2019). "Since the homeostasis of mtDNA in slow‐cycling cells (such as CSC) depends on the mitochondrial deoxynucleoside salvage pathway, we hypothesized that DGUOK depletion might inhibit lung cancer tumor growth and metastasis through suppressing cancer cell stemness." (PMID 31633874, 2019). "Although DDI as an anti‐cancer agent in Lewi's lung cancer allograft model was only modestly effective, it is possible that more potent and specific DGUOK inhibitors based on these anti‐HIV nucleotide analogs could be developed as therapeutics for lung adenocarcinoma patients." (PMID 31633874, 2019). "In lung cancer, NMNAT2 expression was shown to be regulated by deoxyguanosine kinase (DGUOK), a critical enzyme for mitochondrial purine metabolism." (PMID 38396769, 2024). "The DGUOK KO lung cancer cells had increased ADP and decreased ATP levels, which resulted in about a twofold increase in ADP/ATP ratios, suggesting that DGUOK depletion resulted in energy stress in these cells (Fig EV4C)." (PMID 31633874, 2019). "To further investigate the role of DGUOK in CSC self‐renewal, we determine the effects of DGUOK depletion on lung sphere formation in lung cancer cell lines and patient‐derived lung adenocarcinoma cells (PDCs)." (PMID 31633874, 2019). "Lung adenocarcinoma specimens with high DGUOK expression levels also tend to have increased YAP1 staining, which is consistent with the notion that DGUOK regulates YAP1 in lung cancer patients." (PMID 31633874, 2019). "DGUOK KO also inhibited lung cancer cell migration and invasion without affecting the expression of epithelial–mesenchymal transition markers." (PMID 31633874, 2019). "However, our data are not able to rule out the possibility that DGUOK might also play a role in the larger population of lung cancer cells." (PMID 31633874, 2019).
Hypoglycemia (3 papers, 2013 to 2023). A decreased concentration of glucose in the blood. "All reported cases of deoxyguanosine kinase (DGUOK) deficiency with hyperinsulinemic hypoglycemia to date." (PMID 38027095, 2023). "On DOL 25, his metabolic hypoglycemia genetic panel resulted with a biparentally-inherited homozygous likely pathogenic variant in the DGUOK gene (c.749T>C, p.Leu250Ser), consistent with DGUOK deficiency." (PMID 38027095, 2023). "Patients diagnosed with DGUOK mutations present with low birth weight and in a few weeks manifest neurological signs of rotatory nystagmus, hypotonia, and developmental delay, associated with hypoglycemia, raise of lactate and plasma alanine." (PMID 35422763, 2022).